MIR3169 (microRNA 3169)
Synonyms: hsa-mir-3169
Gene: MicroRNA gene on chromosome 13 (61,199,798 to 61,199,880, reverse strand). Ensembl gene ENSG00000266663.
Homologues: Orthologues: chimpanzee MIR3169 (100% identical).